HIF1A (hypoxia inducible factor 1 subunit alpha)
Diseases named in the same sentence as HIF1A in open-access papers (continued):
Sharing a sentence is not in itself a finding about the gene and the disease.
tumor (continued). "In the hypoxic tumour microenvironment, hypoxia inducible factor 1α (HIF‐1α), as a transcription factor, is notably elevated in tumour cells." (PMID 33439514, 2021). "OR7E156P knockdown partially reversed the promotive effects of HIF1A overexpression on tumor growth." (PMID 34422645, 2021). "A nonsense mutation in the BRCA1 associated protein 1 (BAP1) gene has been reported in the post-therapy tumor of a hyperprogressive patient, and the loss of BAP1 expression was highly correlated with HIF-1α expression in uveal melanoma." (PMID 33467713, 2021). "The upregulated PD-L1 induced by hypoxia is generally related to changes in HIF-1α, and many related anti-tumour drugs inhibit PD-L1 expression by downregulating HIF signalling." (PMID 34256773, 2021). "Hypoxia-inducible factor 1a (Hif-1α) was tested by western blot and Immunohistochemical analysis from tumor and surrounding tissue." (PMID 34993150, 2021). "VEGF is one of the downstream effectors of HIF-1α and plays an important role in tumor development and even invasion and metastasis." (PMID 35280249, 2021). "Manipulation of the HIF1A pathway has been proposed as a therapeutic intervention in tumor immunotherapy." (PMID 33777111, 2021). "The TAMs also stabilize and constitutively express HIF-1α under hypoxic conditions that facilitates the recruitment of macrophages to hypoxic regions of the tumor via the secretion of chemokines, such as CCL2 and endothelins (ETs)." (PMID 33230600, 2021). "When looking for crosstalk between MB and HIF-1α especially in the tumor environment, one has thus to pay close attention to the specific oxygenation status and its influence on NO metabolism." (PMID 34671319, 2021). "In the QD-Cat-RGD and RT + QD-Cat-RGD groups, reduced expression of HIF-1α in cell nuclei was observed in tumor tissues." (PMID 34887404, 2021). "Contextually, TH augmented the expression of the hypoxia-related genes HIF1α and CA IX, which shows that TH contributes to tumor angiogenesis and to the response to hypoxic conditions." (PMID 34205977, 2021). "Stability of HIF-1α modulates glycolysis and affects tumor progression, energy production, intracellular acidosis, and angiogenesis." (PMID 33990544, 2021). "Consistently, HIFAL LNA or HIF-1α LNA reduced tumor cell proliferation, denoted by Ki67 staining, in the xenografts as compared with the control animals, while combined treatment with both LNAs further suppressed the cancer cell proliferation." (PMID 33637716, 2021). "For this reason, HIF-1α inhibition represents a hope for halting GB progression and modulating the tumor’s immune microenvironment." (PMID 34830491, 2021). "In turn, inhibition of the HIF-1α signaling pathway in tumor cells has often been a therapeutic goal." (PMID 34868044, 2021). "In Cr(VI)-induced carcinogenesis, miR-143 inhibits tumor growth and angiogenesis by regulating IL-6/HIF-1α in vivo." (PMID 34211501, 2021). "HIF-1α is marked for degradation by a cullin–RING E3 ligase complex in which the von Hippel-Lindau (VHL) tumor suppressor protein acts as the substrate recognition element." (PMID 33682442, 2021). "We confirmed through real-time quantitative polymerase chain reaction (PCR) analysis of tumor homogenate RNA that Hif1α−/− tumors had significant deletion of Hif1α, while transcript levels of Hif2α, the other major HIF pathway signaling factor, was unaffected." (PMID 34556788, 2021). "Instead, tumor cells release lactate that increases the expression of HIF-1α-stabilizing long noncoding RNA (HISLA) in TAMs." (PMID 34078376, 2021). "Taken together, these results suggest that Hif1α in the primary tumor promotes tumor cell dissemination to the bone." (PMID 34556788, 2021).
tumor (continued). "Small molecules including EZN-2968, Topotecan, PX-478, 2-methoxyestradiol, and KC7F2 that inhibit HIF-1α have been developed because tumor hypoxia stabilizes the HIF-1α engaged in VEGF expression and chemoresistance in many solid tumors." (PMID 33230600, 2021). "have revealed that in the presence of pristimerin, the decrease of cell viability under hypoxia is markedly lower than that under normoxia, implying that HIF-1α contributes to tumor resistance." (PMID 34026649, 2021). "Tumor stages and nodal stages had significant correlation with HIF-1α expression and localization of LOXL-2 immunoexpression respectively." (PMID 33639646, 2021). "In tumor tissues, a hypoxic environment results in the expression of hypoxia-inducible factor 1α (HIF-1α), which is known to activate arginase." (PMID 34359568, 2021). "In OS, it was reported that the Glut1 gene is overexpressed in correlation with the hypoxia inducible factor (HIF)-1α to promote tumour progression and is predictive of drug resistance and poor outcome in patients." (PMID 34436447, 2021). "Analysis showed that PRMT3 regulates HIF1/VEGFA signaling pathway and tumor angiogenesis by methylating HIF1α R282 and promoting stability of HIF1α." (PMID 34753906, 2021). "It has been well established that the transcription factor HIF-1α enhances tumor cell motility and invasiveness and contributes to the epithelial–mesenchymal transition (EMT) process, which is crucial for VM formation." (PMID 33850110, 2021). "Studies in animal xenograft models revealed that tumour growth and angiogenesis were repressed by the loss of HIF-1 activity and stimulated by HIF-1α overexpression." (PMID 34154667, 2021). "In HIF-1α-knocked-out murine models, the anti-tumor immune responses of CD8+ TILs improve through the activation of peroxisome-activated receptor α (PPARα) signaling and also elevated metabolism of fatty acids." (PMID 33532902, 2021). "In NSCLC tissues, positive expression of PD-L1 protein was discovered in the cell membrane/cytoplasm of tumor cells, while the HIF-1α protein was basically identified in the cell nucleus, also found in cytoplasm." (PMID 33754005, 2021). "Immunohistochemistry (IHC) is currently used to measure the protein level of HIF1A in a hypoxic cancer tissue, but it needs invasive biopsy of the patient’s tumor and lacks reproducibility and consistency due to inter-observer variability." (PMID 34439934, 2021). "TGCA database presented that HIF-1α expression was significantly down‐regulated in ccRCC tissues compared to that in non‐tumor tissues." (PMID 34926261, 2021). "Hypoxia in the TME alters the IS activity by increasing the resistance of tumor cells to NK cells and to cytotoxic T-cells via the induction of HIF-1α." (PMID 33806300, 2021). "We identify a Stat3/HIF-1α-mediated axis, through which IL-6 executes an anti-tumor role to induce CD40 expression in Mφs." (PMID 34103524, 2021). "We have also reported that hypoxia in the tumor microenvironment suppresses miR-140-5p expression in a Hif-1α-independent manner in BC cells." (PMID 35011574, 2021). "Mechanistically, changed OGT level regulated HIF-1α proteasomal-dependent degradation, the interaction between HIF-1α and pVHL, ER stress-mediated tumor cell survival, and cell metabolism." (PMID 34924561, 2021). "Then, PFA upregulated the oxygen-dependent HIF-1α pathway and induced apoptosis by enhancing the hypoxic tumor environment." (PMID 34592996, 2021). "Although LW6 is known to act by inhibiting the accumulation of HIF-1α, pharmacokinetics needs to be evaluated to assess its potential as an anti-tumor agent." (PMID 33921487, 2021). "On the other hand, high expression of DDIT4 can protect human cancer cells from hypoxia-induced cell death through stabilizing HIF1α in downstream of the suppressed mTOR pathway which followed by occurs increased cell survival and tumor growth." (PMID 34211002, 2021).
tumor (continued). "Hypoxia can also trigger upregulation of Programmed death ligand 1 (PDL1) in tumour cells in a hypoxia-inducible factor 1 alpha (HIF-1α)-dependent manner." (PMID 34956172, 2021). "Firstly, HIF‐1α in fibroblasts has both pro‐tumour and anti‐tumour effects according to the type and malignant degree of cancer." (PMID 33943003, 2021). "Mammary epithelial cell deletion of HIF1α in MMTV-PyMT mice significantly delayed tumor onset, slowed down tumor growth and caused a significant reduction in lung metastases." (PMID 33235291, 2021). "The effect of ES/HA-Tyr + RT on tumor hypoxia and angiogenesis was assessed by the expression of HIF-1α and VEGF-A in xenografted tumor tissues." (PMID 33427520, 2021). "We also observed that besides inducing VEGF-A, TH up-regulates the levels of the HIF1α subunit, which is a key driver of tumor angiogenesis during hypoxia conditions." (PMID 34205977, 2021). "Tumor oxygenation responses to EGFR-TKI therapy appear to be mediated via effects on the hypoxia-regulated transcription factor HIF-1α and downstream expression of VEGF." (PMID 34381712, 2021). "HIF1α transcriptionally regulates many key aspects of tumor development and progression by promoting a more aggressive tumor phenotype, which is characterized by increased proliferation and aggressiveness and neovascularization." (PMID 34385569, 2021). "In accordance with the hyperactivation of the oncogenic EGF/Ras signaling pathway and the rapid tumor progression, Vegfa and Hif1α expression was significantly upregulated in PyMT;Sirt7+/− tumors." (PMID 34433808, 2021). "In agreement with our data, DCA caused a reduction in the tumor microvessel density in treated rats, in which HIF1α suppression was also reported within the tumor cells." (PMID 34830434, 2021). "HIF-1α promotes the adaptive responses of tumor cells to their hypoxic microenvironment through the downstream transcriptional activation of genes regulating tumor survival and progression." (PMID 34440874, 2021). "The IHC results also confirmed that Huaier indeed reduced the expression of HIF‐1α in tumour tissues." (PMID 33377619, 2021). "The PI3K/AKT signaling pathway acts as an intermediate linker in tumor cells, which can be regulated by the proto-oncogene Ras or Src, and can also regulate Myc and HIF-1α activity." (PMID 34046349, 2021). "Hypoxia is a fundamental characteristic of tumor environments and drives HIF1α protein expression in situ." (PMID 34396954, 2021). "The administration of these agents in B16-F10 murine melanoma showed remarkable reduction of tumour blood vessels and enhanced induction of immune cells, together with a reduction of the expression of HIF-1α, increasing treatment efficacy." (PMID 34299503, 2021). "Hypoxia induced HIF-1α expression in tumor cells, followed by metabolic reprogramming, angiogenesis, stromal remodeling, and migration and invasion enhancement." (PMID 34631221, 2021). "For example, in a cohort of 938 HNSCC patients, tumours enriched for hypoxia-responsive genes such as HIF1A, VEGF and carbonic anhydrase IX (CAIX) genes were strongly associated with the lack of CD8+ T-cell infiltrate and immune related gene signatures." (PMID 33923305, 2021). "Aerobic exercise is able to increase the effective perfusion of tumor cells, and leads to a faster degradation of HIF‐1α and inhibits FoxP3+Treg recruitment." (PMID 34387383, 2021). "The HIF-1α and its miRNA target, miR-210, are candidate tumor-drivers of metabolic reprogramming in cancer." (PMID 34293021, 2021). "After microvascular invasion, the tumor will accelerate the release of tumor angiogenesis promoting factors, such as hypoxia-inducible factor-1α (HIF-1α) and vascular endothelial growth factor (VEGF)." (PMID 34712291, 2021). "Contemporarily, HIF-1α is involved in the switching of tumor cells’ energy production from OXPHOS to glycolysis, enhancing invasive qualities of tumor cells." (PMID 33806300, 2021).
tumor (continued). "The hypoxia-inducible factor-1α (HIF-1α) immunohistochemical expression of tumor cells and microvessel density (MVD) of stroma were compared between stroma-low and stroma-high subgroups." (PMID 33810015, 2021). "Inhibition of FAM13A in NSCLC inhibits tumour cell proliferation, FAM13A levels are directly associated with HIF-1α levels, and FAM13A is located downstream of HIF-1α." (PMID 34672860, 2021). "The fluorescent signals in NIR-IIb can be found in the Region 1 in the tumor, which was near the stroma infiltrated with several vasculatures and with weak nuclear HIF-1α immunostaining." (PMID 34887404, 2021). "A large number of studies have shown that HIF-1α plays a central role in the carcinogenesis and progression of pancreatic cancer, and can promote the proliferation, invasion and metastasis of tumor cells." (PMID 34858839, 2021). "In myeloid cells, HIF1α was found to induce the differentiation of TAMs to the M2-lineage and promote tumor angiogenesis by HIF1α-dependent matrix metallopeptidase 9 (MMP9)." (PMID 34575959, 2021). "Hypoxia‐inducible factor signals are usually mediated by two subunits (HIF1α and HIF2α), which mainly affect tumour progression through transcriptional regulation." (PMID 34841698, 2021). "Accordingly, we restricted our analysis of genetic screen data and human cancer samples to acute response genes, which revealed tumor suppressive versus oncogenic roles for different sets of HIF1A targets." (PMID 33654095, 2021). "Many studies also reported that digoxin promoted ROS generation via inhibiting hypoxia-inducible factor-1alpha (HIF-1α), a key regulator of angiogenesis, to block cell growth in a multiple tumor model." (PMID 34539975, 2021). "For example, increased expression of HIF1α was observed in a distant area from the invasive margin, suggesting the presence of hypoxic conditions at the center of the tumor." (PMID 34490110, 2021). "Molecular cooperation between HIF-1α and c-Jun (c-Jun proto-oncogene) was described in NSCLC tumours harbouring an activating mutation of EGFR, resulting in both primary and acquired resistance to EGFR-TKI." (PMID 34298636, 2021). "The hypoxia-inducible factor-1 alpha (HIF-1α) signaling plays a momentous role in the regulation of tumor development, metastasis, recurrence, and drug resistance in the hypoxic tumor microenvironment." (PMID 34917132, 2021). "This in turn leads to aggregation of NADPH oxidase subunits on these lipid rafts resulting in ROS production and increased HIF1α expression adding to the hypoxic tumor conditions." (PMID 34439243, 2021). "Further, the effect of MJ on the expression of HIF-1α, which is considered as the master regulator of tumor metabolism, remains unexplored." (PMID 33716751, 2021). "The inhibition of SDH activity is enhanced by TRAP1 ERK1/2-dependent phosphorylation and has antioxidant and antiapoptotic effects in tumor cells, stabilizing the hypoxia-inducible factor 1α (HIF1α), a transcription factor required for tumor cell growth." (PMID 34829705, 2021). "For example, a human fibroblast cell line with active HIF-1α promotes MDA-MB-231 tumor growth when co-injected in vivo with tumor cells." (PMID 34202979, 2021). "In tumor tissue at 72 h after SDT, a statistically significant decrease in HIF-1α mRNA expression was detected compared to the tumor tissue in the control animal group." (PMID 34681196, 2021). "Various studies have reported that increased levels of HIF-1α stimulate angiogenesis in tumor cells." (PMID 34869321, 2021). "The expression of HIF-1α was relatively high in the control group, implying that the tumor was in a hypoxia state." (PMID 34930284, 2021). "The secretion of macrophage-derived VEGF-A is also markedly increased by HIF-1α at hypoxic sites, thereby enhancing tumor angiogenesis." (PMID 34603327, 2021).
tumor (continued). "An important role for p300 in the HIF-1α pathway has also been documented in clinical BC tumor samples." (PMID 34201346, 2021). "In non-small cell lung cancer (NSCLC) cell lines, the activation of HIF-1α by cMet stimulates the HGF of tumor cells, which leads to ECM degradation, cell dissociation, and increased cell migration through tissue parenchyma." (PMID 34079469, 2021). "Anoxia is one of the major phenomena during tumor growth and activates the HIF-1α transcription factor to upregulate GAPDH expression." (PMID 34650911, 2021). "Meanwhile, topotecan, a FDA-approved topoisomerase I inhibitor, has been shown to inhibit HIF-1α protein accumulation through a DNA damage-independent mechanism and thus delay both angiogenesis and tumor growth." (PMID 34603327, 2021). "Increasing evidence has shown that hypoxia-inducible factor-1α(HIF-1α) plays an important role in promoting malignant cell chemoresistance, tumour metastasis, angiogenesis, immunosuppression and intercellular interactions." (PMID 35004308, 2021). "Studies show that Beclin-1 downregulation and HIF-1α overexpression are conducive to tumor progression and metastasis, and therefore portend poor prognosis." (PMID 34917504, 2021). "On the other hand, HIF-1α regulates the expression of natural killer group 2 member D (NKG2D) ligands to enhance tumor immunosurveillance by NK and γδ T cells." (PMID 34692527, 2021). "Within a hypoxic TME, TAMs participate in angiogenesis and tumor spread due to the upregulation of hypoxia-inducible factor (HIF)-1α and HIF-2α." (PMID 34988021, 2021). "In particular HIF2α is considered an oncogene in ccRCC, while HIF1α likely has a tumor suppressor function and is lost due the frequent deletion of chromosome 14q." (PMID 33803184, 2021). "Subsequent studies showed that Salmonella can also inhibit tumor angiogenesis through AKT/mTOR pathway by suppressing the levels of HIF-1α and VEGF." (PMID 33717106, 2021). "Under hypoxia, tumor cells can enhance the expression of glycolysis gene by upregulating HIF-1α and promote the formation of acidic microenvironment." (PMID 34858839, 2021). "In 2016, Valsecchi and colleagues showed that this interaction is regulated by HIF-1α and promotes tumor survival and tumor propagation." (PMID 34572746, 2021). "HIF-1α siRNA downregulates HIF1α expression in the hypoxic tumor region, ultimately relieving hypoxia-induced ROS generation during PDT and thus improves the overall therapeutic outcome." (PMID 34522227, 2021). "Solid tumors in the hypoxia microenvironment are often regulated by HIF-1α, a master regulator of metastasis, and HIF-1α regulates tumor proliferation, survival, invasion, and angiogenesis." (PMID 34948250, 2021). "As a key regulator, HIF-1α mediates tumor proliferation 6, angiogenesis 7, tumor invasion and metastasis 8, inducing RT resistance." (PMID 33408777, 2021). "MTAs disturb hypoxia-inducible factor 1α (HIF-1α) protein trafficking and function, impairing tumor angiogenesis." (PMID 34830812, 2021). "Catalase can catalyze the in situ production of O2 to relieve the hypoxic tumor microenvironment, and antisense DNA can downregulate HIF-1α to enhance PDT efficacy." (PMID 34168817, 2021). "HIF-1α and HIF-2α can lead to the induction of programmed death-ligand 1 (PD-L1) and the infiltration of tumor-associated macrophages (TAMs), respectively, thereby limiting anti-cancer immunity." (PMID 34575983, 2021). "Immunohistochemical staining of USP29 and HIF1α on tumor sections confirmed that the siRNA-mediated knockdown of USP29 not only efficiently depleted USP29 but also reduced HIF1α levels." (PMID 34272356, 2021). "With growing studies in tumor glucose metabolism, it has been realized that its increased activity is one of the major consequences of certain oncogenic drivers, among which HIF1α signaling represents the main pathway involved." (PMID 34836938, 2021).